APOE (apolipoprotein E)
Diseases named in the same sentence as APOE in open-access papers (continued):
Sharing a sentence is not in itself a finding about the gene and the disease.
dementia (continued). "SCA revealed variable dementia risks by subtype and age, with associations for TBI and APOE e4/e4 robust to model specification; in contrast, diabetes showed fluctuating links with dementia subtypes." (PMID 38807092, 2024). "The effect of APOE ε4 on dementia risk can be modified by other factors, including genetic and environmental factors." (PMID 38792885, 2024). "Relatedly, our method of incorporating various combinations of risk factors, such as TBI, APOE e4/e4, hypertension, etc., indicates that these robust association risk factors should be evaluated collectively to assess dementia risk and diagnosis accurately." (PMID 38807092, 2024). "AUCs further improved to 0.800, 0.827, and 0.793 for the outcomes of all-cause dementia, AD, and VD, respectively, when APOE ε4 carrier status was added to the CAIDE model (Model 2)." (PMID 39160600, 2024). "The APOE allele status has been associated with both PD onset and its progression to Parkinson’s disease dementia (PDD)." (PMID 38528629, 2024). "When combined with clinical biomarkers (apolipoprotein E ε4 allele count, memory, executive function), a model including aBA and aFI predicted 5-year dementia risk among MCI patients with an out-of-sample AUC of 0.88." (PMID 39446224, 2024). "The effect of excessive sugar intake on all-cause dementia and AD was more prominent in APOE-ε4 alleles carriers, potentially partly owing to the complex interplay between sugar intake and metabolism disturbances." (PMID 39020335, 2024). "Individuals who were homozygous for the apolipoprotein ε4 (APOE ε4) allele were 5 to 9 times more likely to die with dementia." (PMID 38709531, 2024). "In the APOE ε4 status-specific analyses, generally, the effect of sugar intake on all-cause dementia and AD was likely to be more prominent among participants with one APOE ε4 allele." (PMID 39020335, 2024). "Susceptibility factors are baseline factors include advanced age (> 65 years), frailty, lower level of education, preoperative cognitive decline or dementia, carrying the apolipoprotein E ε4 variant, and metabolic syndrome (obesity, diabetes, etc.)." (PMID 38649932, 2024). "In a meta-analysis of the relationship between the APOE gene and PD dementia, the dementia risk of those with the APOE ε4 allele was 1.72 times greater than that of those without ε4." (PMID 38792885, 2024). "A recent study of a mixed sample of > 3900 CN and MCI individuals with no biomarkers found that apathy (regardless of other NPS) contributed to a higher risk of developing dementia in APOE e3 carriers compared to e4 carriers." (PMID 38279143, 2024). "Although advanced age is the most important risk factor for dementia, education and socioeconomic status; genetic factors, particularly the apolipoprotein E (APOE) e4 allele; and a variety of health conditions are also risk factors." (PMID 38271405, 2024). "In a multivariate logistic regression model, only age, total cholesterol (inversely), physical activity (inversely) and APOE genotype were statistically significantly associated with all-cause dementia." (PMID 38570813, 2024). "In these non-AD cases, Aβ levels, as measured by Aβ-PET, also increase with age and APOE ε4 carrier status but vary in cortical distribution relative to the underlying dementia diagnosis." (PMID 38279230, 2024). "Contrary to previous reports from smaller studies, genetic risk factors for dementia, including APOE genotype and AD-PRS, have a minimal impact on cognition in healthy individuals." (PMID 38745010, 2024). "In the literature, there are divergences regarding the link between APOE status, wine consumption, and the risk of dementia." (PMID 39458427, 2024). "Low plasma levels of ApoE have been associated with an increased risk of dementia, with higher levels linked to a higher risk of ischemic heart disease." (PMID 38673634, 2024).
dementia (continued). "In this context, an additive interaction between apathy and the APOE e4 allele has been previously demonstrated for dementia risk among individuals with MCI." (PMID 38473892, 2024). "In the vascular dementia comparison, the APOE e4/e4 has a higher OR in the unattributed dementia cause group than in vascular dementia." (PMID 38807092, 2024). "Another study confirmed that the APOE ε4 allele is a major risk factor for the development of Parkinson’s disease dementia (hazard ratio = 2.41)." (PMID 38792885, 2024). "Amongst those with APOE genetic categories (e3/e4, and e4/e4) linked to dementia the results were unchanged." (PMID 38456089, 2024). "First of all, data regarding SCD and genetic predisposition for dementia, beyond APOE ε4, are heterogeneous." (PMID 38534745, 2024). "APOE is a well-known risk factor for dementia, especially AD, and a fundamental component in most dementia risk prediction models." (PMID 39160600, 2024). "In this cohort study of cognitively healthy elderly individuals, we found that sleep disruption is linked to future dementia, particularly in APOE ε4 carriers, which was partially explained by the increased plasma NfL concentrations." (PMID 38421124, 2024). "The Apolipoprotein E (APOE) ε4 allele is the strongest genetic risk factor for dementia caused by sporadic Alzheimer’s disease (AD), and is present in 9–23% of various ethnic populations." (PMID 38230714, 2024). "The causes of dementia are varied, but genetic variations in the apolipoprotein E (ApoE) gene have been identified as major factors contributing to the disease." (PMID 38764503, 2024). "In our study with ~ 50,000 participants, we found robust correlations between peripheral GFAP and NfL expression with AD-GRS APOE*E4 alleles, suggesting shared genetic factors driving early neuroinflammation and neurodegenerative changes in dementia." (PMID 38735950, 2024). "A more comprehensive understanding of the underlying mechanisms of dementia has been made possible by the discovery of other genetic variables linked to the disease, beyond APOE." (PMID 38607741, 2024). "Of the total population, 56% had at least one APOE ε4 allele and 95.7% were clinically diagnosed with AD or some other form of dementia before death." (PMID 38663907, 2024). "In the present study, we sought to determine the potential involvement of oxysterols in lipid‐dementia associations by investigating relationships of plasma oxysterols with APOE, serum lipids, and incident dementia and cognitive impairment in WHIMS." (PMID 38574442, 2024). "Of particular significance were traumatic brain injury (TBI) and the APOE e4/e4 allele, which demonstrated consistent associations with all examined dementia subtypes across all analytical conditions." (PMID 38807092, 2024). "The APOE ε4 allele is associated with increased cerebral amyloid-β pathology, but its effect on dementia is mediated by the severity of AD pathology." (PMID 38792885, 2024). "Dozens of significant dementia-associated genes have been identified, including APOE, APOC1, and TOMM40." (PMID 38542318, 2024). "In participants from the Framingham Heart Study, depression increased the risk of incident dementia over a 17-year follow-up, even after controlling for other risk factors for dementia including apolipoprotein E status." (PMID 39061462, 2024). "In the same vein, work with high job control acts differently on the effect of the APOE ɛ4 allele in dementia for men and women by reducing the associated risk in men while producing an opposite pattern in women." (PMID 38424518, 2024). "For example, in the age- and gender-adjusted model, APOE e4/e4 has significant ORs, from high to low, in AD (5.09 [2.92–8.87]), all-cause dementia (3.85 [2.82–5.24]), and unattributed cause dementia (3.08 [1.93–4.9]) among the midlife participants." (PMID 38807092, 2024).
dementia (continued). "These encompass tau deposition in the MTL, Aβ in the medial parietal lobe, and vascular pathology, all of which are associated with family history of dementia, APOE ε4, and CAIDE score." (PMID 38421123, 2024). "In a Cox regression model adjusted for all CAIDE model variables, age and APOE ε4 carrier status in Model 2 were statistically significantly associated with all dementia outcomes." (PMID 39160600, 2024). "Cluster 1 mainly presented alterations in MAPT and a higher percentage of people with APOE e4 allele (therefore, with a higher risk of developing dementia due to AD), as well as higher tau levels at the dementia stage." (PMID 38693203, 2024). "The apolipoprotein E (APOE) gene, located on chromosome 19q13, is the most replicated genetic association within dementia research and within DLB." (PMID 38334615, 2024). "MET-FINGER aims to test a FINGER 2.0 multimodal intervention, combining an updated FINGER multidomain lifestyle intervention with metformin, where appropriate, in an APOE ε4-enriched population of older adults (60–79 years) at increased risk of dementia." (PMID 38297399, 2024). "In line with previous studies, we showed that APOE e4 is the strongest risk factor for dementia in Lewy body diseases." (PMID 38978726, 2024). "After further stratifying by APOE e4 status, BB genotype with two APOE e4 alleles showed even stronger association with all-cause dementia 4.29 (1.57, 11.72) and other types dementia (5.49, 1.70-17.69) in males." (PMID 38863509, 2024). "Normal cognitive, elderly individuals carrying the APOE ε4 allele show a sevenfold higher risk of developing MCI or dementia." (PMID 38421124, 2024). "The ability of CR to mitigate dementia risk attributable to APOE‐ε4 allele has been reported previously, and our findings extend the previous work by simultaneously taking into account other transitions across the cognitive continuum, as well as death." (PMID 38779828, 2024). "Another data-driven approach to developing a dementia risk prediction model highlighted the significant predictive power of age and apolipoprotein E status, with very limited increases in model performance after including more factors into the model." (PMID 39302374, 2024). "In our sample, being a current smoker or having diabetes doubled the risk, and being a carrier of at least one APOE ε4 allele tripled the risk of dementia." (PMID 38865433, 2024). "Women with dementia reported an increased prevalence but decreased mortality, confirming the sex differences in dementia risk factors, including the APOE gene, stroke, and hypertension." (PMID 39238546, 2024). "Before stratifying by sex and APOE status, compared to OO genotype, BB genotype was associated with increased risk of all-cause dementia (1.36, 1.03-1.80) and other types dementia (1.65, 1.20-2.28)." (PMID 38863509, 2024). "Although genetic factors are associated with a higher risk of developing dementia, such as the apolipoprotein E (APOE) genotype, recent research has shown that an individual’s lifestyle plays a significant role in the risk of developing AD." (PMID 39038282, 2024). "More importantly, using the AD-GRS and APOE*E4 allele number, we identified potential shared genetic factors between dementia, GFAP, and NfL expression." (PMID 38735950, 2024). "Hearing loss in midlife (age 45–65 years) has been associated with cognitive decline and dementia, especially in those individuals with ApoE ε4." (PMID 39064140, 2024). "In this study, APOE ε4 genotype modified the associations of skin AGEs and dementia such that the associations were more pronounced among carriers." (PMID 38218902, 2024). "AD and DLB, while both presenting dementia as the main clinical symptom, share APOE and BIN1 (bridging integrator-1) as risk genetic loci." (PMID 38528629, 2024). "In the future, we hope to enroll more dementia cases to figure out the role of the APOE ε4 allele in hearing loss and PD." (PMID 38792885, 2024).
dementia (continued). "In males, BB genotype was consistently associated with increased risk of dementia, especially in those with two APOE e4 alleles." (PMID 38863509, 2024). "Patients carrying APOE ε4 had a higher prevalence of dementia and hearing loss, which is in keeping with numerous reports in the last three decades." (PMID 38792885, 2024). "In all three groups, individuals with both Sleep+ and APOE+ have significantly higher dementia risk compared to the control group (Sleep−/APOE−), and individuals with Sleep+/APOE+ also have higher risk than those with Sleep−/APOE+." (PMID 38421124, 2024). "We therefore used two genetic tools for AD, the AD-GRS and the number of APOE*E4 alleles carrying as independent variables, to explore the association between genetic of dementia and GFAP or NfL." (PMID 38735950, 2024). "Individuals carrying the APOE ε4 allele have increased risk of developing AD as well as other forms of dementia, including PD dementia and Lewy body dementia." (PMID 38792885, 2024). "Older age, genetic factors, traumatic head injury, depression, cardiovascular and cerebrovascular disease, smoking, family history of dementia, increased homocysteine levels and Apolipoprotein E (APO-E) ε4 allele have been recognized as potential risk factors." (PMID 38519775, 2024). "An association between APOE ε4 and increased AD and related dementia risk was recently reported in global Hispanic populations, with the strength of this association varying across Hispanic subgroups." (PMID 39335404, 2024). "The APOE-ε4 isoform is associated with a greater risk of dementia, and it is considered to promote the aggregation of amyloid-β (Aβ)." (PMID 38334615, 2024). "For example, a large number of studies have confirmed that the APOE gene is a high-risk genetic factor for progression of dementia." (PMID 39026589, 2024). "PD patients carrying APOE ε4 were found to have faster cognitive decline and were at higher risk of progression to dementia." (PMID 38792885, 2024). "We have also earlier seen in the Betula cohort that the connection between particulate air pollution and dementia exhibited greater strength among participants with the APOE ε4 allele and among those with lower scores on odor identification ability." (PMID 39193206, 2024). "Research has indicated a relationship between higher plasma levels of HDL-C and ApoE levels and a lower risk of dementia." (PMID 39421569, 2024). "For example, the apolipoprotein E (APOE) gene is a well-studied risk factor for AD and related dementias, however, its prevalence and influence on disease risk varies significantly among ancestral groups." (PMID 38859922, 2024). "Among them, only CD34+CD133+ EPCs, but none of the other cell types, significantly impacted the risk of AD (HR = 0.64, P = 0.02) and all-cause dementia (HR = 0.63, P = 0.006) after adjusting for age, sex, years of education, APOE ε4, and vascular diseases." (PMID 38854406, 2024). "Higher vitamin D and grip strength were associated with a lower risk of dementia, and seemed to halve the adverse effects of APOE e4 genotype on dementia." (PMID 37246226, 2023). "As supported by previous literature focusing on SCD, combining APOEε4 + with SCC led to substantially increased odds of incident dementia as compared to those associated with SCC alone or APOE ε4 + alone." (PMID 37951931, 2023). "Instead, low plasma apoE levels were shown to be directly associated with an increased risk of AD and all types of dementias, whereas higher levels appeared protective." (PMID 37400888, 2023). "Dementia is of highly heritable, and emerging evidence demonstrated that apolipoprotein 4 (APOE e4) genotype is the most common genetic risk factor for dementia." (PMID 37246226, 2023). "In the present study, we aimed to investigate the associations of APOE ɛ4/ε4 with both CSF and plasma biomarkers in dementia and biomarker diagnosed AD." (PMID 37065463, 2023).
dementia (continued). "In contrast, previous studies from the United States reported a stronger association between APOE ε4 and dementia risk for women than men." (PMID 36790027, 2023). "Consistent with our findings, post-mortem studies have found that APOE e4 was associated with dementia in LBD in both “pure” LBD and those with AD co-pathology." (PMID 37987016, 2023). "The diagnosis of dementia mediates the effect of APOE-ε4 status on other causes of mortality in women with the percent mediated being 34%; though the p value was .061." (PMID 37434484, 2023). "Further, 54.2% were diagnosed with dementia prior to death, and 38.6% had at least one APOE ε4 allele." (PMID 37269007, 2023). "Further, there was little evidence indicating a sex difference (RHR, 0.88 [0.72, 1.07]), or an effect modification by age or region on the sex difference, in the effect of APOE ε4 carriage and all‐cause dementia." (PMID 36790027, 2023). "Overall, these findings support a role for lower apoE glycosylation on cerebral Aβ accumulation before the onset of dementia, potentially acting as a risk factor for AD dementia in those carrying the Ɛ4 allele." (PMID 37221560, 2023). "The inclusion of Z1b indicates that low education and APOE ε4 are insufficient on their own to cause dementia." (PMID 38435670, 2023). "Our result confirms that the mean biennial %WC loss is a strong predictor of dementia; the odds ratio is almost equivalent to that of having a single APOE ε4 allele (i.e., ε3/ε4 populations)." (PMID 37628615, 2023). "Our analyses further support that the effect of APOE-ε4 on the risk for other causes of mortality is mediated by approximately up to one-third through dementia diagnosis." (PMID 37434484, 2023). "Although APOE4 was found to be significantly associated with memory function in non-dementia elderly individuals, APOE genotyping remains the most common risk factor utilised to test for sporadic AD risk, and in clinical diagnosis." (PMID 37686283, 2023). "A comparison of individuals with dementia (N = 151) and age-matched controls (N = 165) showed a significantly higher occurrence of the “L” allele with APOE Ɛ4 carriers and dementia (p < 0.0001)." (PMID 38028602, 2023). "ApoE ε2 is often associated with the onset of dementia occurring later in life, while ApoE ε4 is typically associated with an earlier onset of the disease and a more severe form of dementia progressing over time." (PMID 38137454, 2023). "HDL-c and APOE have been associated with brain function, dementia, and AD in observational studies, mainly due to the apolipoproteins involved in the deposition and clearance of β-amyloid, a causal factor for neurodegeneration." (PMID 37190655, 2023). "The APOE locus was a notable exception, where we observed an association between the high-confidence fine-mapped signal rs429358 and increased risk for dementia across all four populations examined." (PMID 37425708, 2023). "We analyzed the associations of APOE ε4/ε4 on CSF and plasma biomarkers in dementia and biomarker diagnosed AD." (PMID 37065463, 2023). "Second, we investigated the extent to which the potential relationships of APOE-ε4 status with all-cause mortality, and cause-specific mortality were mediated by dementia diagnosis." (PMID 37434484, 2023). "We defined genetic risk for dementia using a comprehensive polygenic risk score whereas most previous studies have explored gene-diet interactions for individual genetic variants (e.g., APOE genotype)." (PMID 36915130, 2023). "Both variations yielded the same polymorphisms, including a well-known marker of dementia, rs429358in the APOE gene." (PMID 37953886, 2023). "The risk of dementia was higher among APOE ɛ4 carriers experiencing a large BMI gain (9.93 [3.49−24.6]) or loss (6.66 [2.83−14.4]) than APOE ɛ4 noncarriers with stable BMI." (PMID 35921193, 2023).